ZNF778 (zinc finger protein 778)
Description:
May be involved in transcriptional regulation.
Synonyms: FLJ31875
Tractability: PROTAC: ubiquitination databases record sites on it.
Gene: Protein-coding gene on chromosome 16 (89,217,692 to 89,237,141, forward strand). Ensembl gene ENSG00000170100.
Subcellular location: Nucleus
Subcellular location (Human Protein Atlas): Nuclear bodies; Nucleoplasm
Pathways (Reactome):
Gene expression (Transcription): Generic Transcription Pathway; Regulation of endogenous retroelements by KRAB-ZFP proteins
Gene Ontology:
Molecular function: protein binding; DNA-binding transcription factor activity, RNA polymerase II-specific; RNA polymerase II transcription regulatory region sequence-specific DNA binding
Biological process: regulation of transcription by RNA polymerase II; regulation of DNA-templated transcription
Cellular component: nuclear body; nucleoplasm; nucleus
Genetic constraint (gnomAD): Loss-of-function variants: 27 observed, 18.43 expected, observed/expected ratio (o/e) 1.46, 90% interval 1.07 to 1.89. The synonymous counts are far from expectation, so gnomAD's model fits this gene poorly and the ratio says little. Missense variants: 1,201 observed, 893.34 expected, observed/expected ratio (o/e) 1.34, 90% interval 1.28 to 1.41. Synonymous variants: 452 observed, 332.75 expected, observed/expected ratio (o/e) 1.36, 90% interval 1.26 to 1.47.
Homologues: Orthologues: chimpanzee ZNF778 (97% identical), macaque ZNF778 (89% identical), mouse Zfp763 (34% identical), rat Zfp763 (34% identical). Paralogues in human: ZNF266 (43% identical), ZNF560 (32% identical), ZNF555 (31% identical), ZNF846 (31% identical), ZFP90 (29% identical), ZFP37 (29% identical), ZNF20 (29% identical), ZNF69 (29% identical), ZNF599 (29% identical), ZNF805 (28% identical), ZNF77 (28% identical), ZNF264 (28% identical), and 50 more.
Diseases named in the same sentence as ZNF778 in open-access papers:
ZNF778 is named in the same sentence as 6 diseases in open-access papers, as found by Europe PMC text mining. Sharing a sentence is not in itself a finding about the gene and the disease. The quoted sentences say what the papers report.
cognitive disorder (2 papers, 2020 to 2025). A disease affects cognitive processes. "Unlike this trend, some KRAB-ZNFs linked to cognitive disorders were human specifically upregulated, e.g., ZNF778, a candidate gene for autism spectrum disorder and cognitive impairment, and ZNF267, which is upregulated in the prefrontal cortex of AD patients." (PMID 40928843, 2025). "Microdeletion of 16q24.3 is associated with ASD because it affects ankyrin repeat domain 11 (ANKRD11) and zinc finger protein 778 (ZNF778) genes, leading to cognitive impairment and brain abnormality." (PMID 32244359, 2020).
KBG syndrome (1 paper, 2017). KBG syndrome is a rare condition characterized by a typical facial dysmorphism, macrodontia of the upper central incisors, skeletal (mainly costovertebral) anomalies and developmental delay. "In this sense, haploinsufficiency for ZNF778 may also contribute to the higher frequency of CHDs, essentially VSDs, present in the 16q24 microdeletion syndrome compared with KBG syndrome." (PMID 28422132, 2017).
melanoma (1 paper, 2023). A malignant, usually aggressive tumor composed of atypical, neoplastic melanocytes. "Another TF, ZNF778, was also a strong predictor of regorafenib cell viability; the ZNF778 promoter has also been found to be highly mutated in melanoma." (PMID 36894939, 2023).
ventricular septal defect (1 paper, 2021). The presence of a defect (opening) in the septum that separates the two ventricles of the heart. "Haploinsufficiency for ZNF778, which is extensively expressed in the brain and the heart, may contribute to the higher frequency of ventricular septal defects present in the patients with 16q24 microdeletion syndrome." (PMID 34604130, 2021).
ZNF778 also shares sentences with these, for which no sentence is quoted: autism spectrum disorder (1 paper); COVID-19 (1).